CXCL8 (C-X-C motif chemokine ligand 8)
Diseases named in the same sentence as CXCL8 in open-access papers (continued):
Sharing a sentence is not in itself a finding about the gene and the disease.
prostate carcinoma (continued). "Two of the most frequently studied cytokines and chemokines in relation to prostate cancer development and pathophysiology are Interleukin-6 (IL6) and C-X-C motif chemokine ligand 8 (CXCL8)." (PMID 30473726, 2018). "CXCL8 was identified as a downstream target of DACH1 in the process of suppression of cell proliferation and migration in breast and prostate cancer." (PMID 29636079, 2018). "In prostate cancer, it has been demonstrated that DACH1 was negatively correlated with the expression of CXCL8 and able to antagonize the effects of CXCL8 on cellular migration." (PMID 29636079, 2018). "Our prior studies demonstrated that silencing of PTEN expression increased the transcription and secretion of CXCL8 and increased gene expression of the receptors CXCR1 and CXCR2 in prostate cancer cells." (PMID 24970800, 2014). "We investigated the role of CXCL8, CCL2 and CXCL12 in regulating the growth and survival of prostate cancer cells, independently or in a co-dependent manner." (PMID 24970800, 2014). "We propose these results indicate the importance of CXCL8-driven CXCR4 and CCR2 expression in the prostate cancer cells, which increases their capacity to respond to each of these stromal-derived chemokines." (PMID 24970800, 2014). "Subsequently, our group demonstrated that autocrine CXCL8 signaling confers resistance to the DNA-damaging agent oxaliplatin, the death receptor agonist TRAIL and anti-metabolites in prostate cancer cells." (PMID 24276377, 2013). "Reports from various groups have demonstrated that CXCL8 signaling activates multiple transcription factors such as NFκB, AP-1, HIF-1 and STAT3, and in prostate cancer cells, this signaling has been shown to induce activation of the androgen receptor (AR)." (PMID 24276377, 2013). "Our study found that cell models of advanced prostate cancer demonstrated constitutive expression of STAT-3, and also exhibited characteristics such as a high secretion of growth factors, such as VEGF and cytokines, such as IL-6 and CXCL8." (PMID 35465350, 2022). "In the treatment of prostate cancer with oxaliplatin, the expression of CXCL1, CXCL8 and CXCR2 were significantly increased, while CXCR2 inhibitors could enhance the cytotoxicity of oxaliplatin and achieve the combined anti-tumor effect." (PMID 33814009, 2021). "We observed the increased expression of CXCL8, CCL2, CXCL10, and CCL20 in prostate cancer tissues induced by intraprostatic injection of LNCaP cells stably transfected with SFMBT2 shRNA compared with prostate tissues injected with LNCaP cells stably transfected with control shRNA." (PMID 32971847, 2020). "Also, the expression level of CXCL8, CCL2, CXCL10, and CCL20 was proportionally related to a high Gleason score of ≥8, which seems closely related to prostate cancer invasion and metastasis." (PMID 32971847, 2020). "Moreover, chemokines (i.e., CXCL8/IL-8, CXCL12) overexpressed in prostate carcinoma activate proliferation-related pathways and stimulate angiogenesis, recruit immune cells infiltrating into cancerous foci, and trigger tumor-associated inflammation." (PMID 31500632, 2019). "Additional findings supporting the hypothesis of C. acnes as a trigger of prostate cancer development comes from in vitro studies reporting an increased secretion of IL6 and CXCL8 by prostate epithelial cells infected with C. acnes." (PMID 30473726, 2018). "Levels of IL6 and CXCL8 in pre-operative serum samples were analyzed using ELISA, and concentrations were compared between prostate cancer patients with and without prostatic C. acnes infection using standard statistical methods." (PMID 30473726, 2018). "Thus, our experiments indicate that CXCL8 and CXCL12 signaling co-operate to accelerate the migration of prostate cancer cells." (PMID 24970800, 2014). "Our current findings propose that tumor-derived CXCL8, through the regulation of fibroblast-derived CXCL12 production, may drive immune evasion in prostate cancer." (PMID 24970800, 2014).
prostate carcinoma (continued). "Moreover, we have confirmed that exposure to 5-FU potentiates this level of CXCL8 signaling by concurrently inducing CXCL8 secretion and up-regulating CXCR1 and CXCR2 gene expression in metastatic prostate cancer cells." (PMID 22590561, 2012). "In addition, expression of CXCL8, CCL2, CXCL10, and CCL20 was also increased in prostate cancer tissue induced by intraprostatic injection of LNCaP cells stably transfected with SFMBT2 shRNA and in the tissue of prostate cancer patients." (PMID 32971847, 2020). "CXCL8 did not promote migration of prostate cancer cells; elevated secretion of CXCL8 by prostate tumors results in locally high levels of this chemokine which in turn may prevent the establishment of a chemotactic CXCL8 gradient." (PMID 24970800, 2014). "For example, anti-CXCL8 antibodies have been used to impede the growth of PC3 tumors in SCID mice by reducing angiogenic signaling and have been shown to diminish angiogenesis in orthotopic prostate carcinomas in NOD-SCID mice, as a result of impaired neutrophil infiltration." (PMID 24276377, 2013). "The role of GRO expression in prostate cancer cells was revealed in the murine TRAMP-C2 cell model, lacking expression of CXCL8 and overexpressing CXCL1." (PMID 39594640, 2024). "On the other hand, CXCL1, but not anti-CXCL8, was found to be responsible of mediating tumor-derived angiogenesis in human DU145 prostate cancer cell line." (PMID 24971349, 2014).
pancreatic cancer (270 papers, 2002 to 2026). "Ala Litman and coworkers explained the importance of the CXCL8-CXCR2 axis in pancreatic cancer, which indicate that the serum chemokine CXCL8 is a better diagnostic and predictive marker than CXCR2, C-reactive protein, classic CA 19-9, and CEA protein." (PMID 35468838, 2022). "CXCL8 released from pancreatic cancer induces muscle atrophy to cause involuntary body weight loss or cachexia in patients." (PMID 35011369, 2021). "Doses of at least 4 Gy induced module 1 (e.g., CCL5, CXCL10) and module 4 (e.g., CCL20, CXCL8) chemokines in pancreatic cancer cells, with larger effects using higher radiation doses." (PMID 40811032, 2025). "At the same time, the cytokines, such as IL-6, IL-8, CXCL12, and CXCL8, secreted by CAFs, have also been proven to be important factors in suppressing the anti-tumor immune response of pancreatic cancer." (PMID 41156387, 2025). "In tumor xenograft models, using human pancreatic cancer cell lines, CXCL8 expression was correlated with a preferential expansion of CXCR2+CD68+ macrophages, which significantly led to the decreased efficacy of anti-PD1 therapy." (PMID 38339310, 2024). "Recently, studies have demonstrated that CXCL8(IL-8) is a proangiogenic chemokine in pancreatic cancer and TNBC, playing a role through HUVECs." (PMID 39075612, 2024). "While constitutively expressed by a plethora of pancreatic cancer cell lines, CXCL8 is interesting in that its secretion by cancer cells is greatly upregulated due to interactions between pancreatic cancer cells and other cell types in the PDAC TME." (PMID 38339310, 2024). "Significantly, CXCL8 secretion by the tumor cells stimulated and maintained the survival of CAFs, highlighting its beneficial role to pancreatic cancer cells." (PMID 38339310, 2024). "The inflammatory cytokines TNF-α and LIF influence the CXCL-8 expression in pancreatic cancer progression." (PMID 35887223, 2022). "Elevated CXCL8 secretion was detected in the medium of pancreatic cancer cell lines derived from liver metastases, in comparison with immortalized pancreatic ductal epithelial cells." (PMID 35574410, 2022). "In vitro studies of pancreatic cancer have shown that CXCL8 works synergistically with CXCL12 to promote angiogenesis and invasion." (PMID 35879507, 2022). "CXCL8 was significantly expressed at high levels in 19 unique analyses in colon cancer and 3 unique analyses in pancreatic cancer." (PMID 34439306, 2021). "Overexpressed CXCL8 in pancreatic cancer mediates CXCR2+CD68+ macrophage trafficking to the TME and contributes to cancer progression and PD-1 blockade resistance." (PMID 35011369, 2021). "Activated pancreatic stellate cells enhance pancreatic cancer fibrosis and progression through paracrine CXCL8." (PMID 35011369, 2021). "Senescent CAFs are a pathologically relevant fibroblast population that secrete excess CXCL8 to promote pancreatic cancer invasion." (PMID 35011369, 2021). "In gemcitabine-refractory patients with pancreatic cancer, plasma CXCL8 is a useful circulating biomarker for predicting resistance to nanoliposomal irinotecan therapy." (PMID 35011369, 2021). "A mechanism study found that IFN-γ suppresses the expression of CXCL8 in pancreatic cancer and inhibits TAMs migration to enhance anti-PD1 efficacy." (PMID 35011369, 2021). "TAMs secrete CXCL8 to promote pancreatic cancer cell migration and invasion through the signal transducer and activator of transcription 3 (STAT3) pathway." (PMID 35011369, 2021). "Pancreatic cancer cell increases CXCL8 secretion to enhance angiogenesis and acquisition of gemcitabine resistance." (PMID 35011369, 2021). "We have obtained similar results in our studies investigating serum CXCL-8 levels in pancreatic cancer (PC) patients, where significantly elevated CXCL-8 concentrations were revealed in PC patients in comparison to healthy controls." (PMID 32192002, 2020).
pancreatic cancer (continued). "Consistently, CXCL8 has also been a strong predictor for poor outcome in various treatments including chemo-immunotherapy in pancreatic cancer or aflibercept therapy in metastatic CRC." (PMID 31991604, 2020). "Overexpression of Brachyury causes EMT in human pancreatic cancer cell lines, along with enhanced expression of CXCL8, CCL5, and CXCL1, while the inhibition of CXCL8 signaling pathway abrogates Brachyury-induced EMT phenotypes and invasive capacity of cells." (PMID 24966464, 2014). "Cyclin E1, epithelial growth factor (EGF), IL-6, CXCL8, IL-10, and IL-1RA have all been shown to be elevated in individuals with pancreatic cancer and high IL-6 or IL-10 levels correlated to poor survival." (PMID 20214814, 2010). "Importantly, CXCL8 has been found to be constitutively expressed in a variety of solid tumors, including melanoma, glioma, and colon and pancreatic cancer." (PMID 38339310, 2024). "Thus, CXCL8 appears beneficial to pancreatic cancer by promoting the angiogenesis and vascularization of the PDAC TME." (PMID 38339310, 2024). "In addition, studies have demonstrated that the Il-8(CXCL8)/CXCR2 axis is involved in tumorigenesis by promoting angiogenesis in metastasized pancreatic cancer and TNBC." (PMID 39075612, 2024). "In addition to the well-known chemotaxis effects on immune cells, CXCL8 has exhibited its promoting effects on angiogenesis in pancreatic cancer and VM formation in glioblastoma." (PMID 35321317, 2022). "Gemcitabine treatment induces senescence in pancreatic cancer cells and increases CXCL8 expression." (PMID 36012531, 2022). "Thus, not only do TME cells, such as CAFs, signal pancreatic cancer cells to secrete CXCL8 for pro-angiogenic effects, but also increase the accumulation of pro-tumorigenic support cells, such as TAMs, highlighting CXCL8’s nefarious role in promoting PDAC tumorigenesis." (PMID 38339310, 2024). "Furthermore, the treatment of pancreatic cancer cells with recombinant CXCL8 could strongly increase extracellular DNA production." (PMID 35574410, 2022). "Moreover, in our previous studies, there were significant differences between CXCL8 concentrations and nodal involvement in patients with pancreatic cancer, while the serum level of this chemokine was statistically higher in subjects with distant metastases than without them in CRC patients." (PMID 34680333, 2021). "However, the high expression of PGE2 and CXCL8 in PDAC patients could reflect the severity of this tumor compared to other pancreatic tumors." (PMID 20214814, 2010). "In pancreatic cancer, the orchestration of anti-tumor immune responses through CXCL8 (IL-8) by radiotherapy is reliant on NK cells." (PMID 38835055, 2024). "NF-κB enhances the secretion of CXCL8 and VEGF to induce angiogenesis in pancreatic cancer cell lines." (PMID 35011369, 2021). "Other members of the C-X-C motif chemokine family were found to be upregulated in pancreatic cancer cells after Rintatolimod treatment, like CXCL 1, CXCL2, CXCL3, CXCL8 (IL-8), CXCL11, CXCL14, and CXCL16." (PMID 34207861, 2021). "CAFs express CXCR2 and respond to paracrine signals of pancreatic cancer cells by upregulating CXCR2 ligands such as CXCL1, CXCL7, and CXCL8." (PMID 35011369, 2021). "For instance, CCR2/CCR5 inhibitors, such as PF-04136309 in pancreatic cancer, could disrupt TAM/Treg recruitment in ESCA, while CXCL8/CXCR2 blockade, trialed in CRC, may reduce MDSC/NET-mediated immunosuppression." (PMID 40134607, 2025). "Also, in pancreatic cancer mouse models, CXCR2+CD68+ macrophages (M2 phenotype) are recruited to the TME by tumor-derived CXCL8, where they contribute to local immunosuppression, thereby reducing the effectiveness of PD-1 blockade therapy." (PMID 38835055, 2024). "This may be the case, e.g., for CXCL8 and CXCL12, which have previously been found to cooperate in stimulating the invasion and proliferation of pancreatic cancer cells." (PMID 39595551, 2024).
pancreatic cancer (continued). "Moreover, pancreatic cancer cells can recruit TANs by secreting chemokines of the CXC family, specifically CXCL6 and CXCL8 or CXCL1–3 and CXCL5–8 that are recognized by CXCR1 or CXCR2 receptors expressed on neutrophils." (PMID 35711414, 2022). "Moreover, pancreatic cancer cells produce cytokines such as IL35 to stimulate the angiogenic activity of TAMs via expression of CXCL1 and CXCL8, while inhibition of this interaction reduces TAM infiltration and microvessel formation." (PMID 34201127, 2021). "MAFs in liver metastases of pancreatic cancer seem to promote angiogenesis and resistance to antiangiogenic drugs through secretion of CCL2 and CXCL8; preclinical studies suggest that targeting MAFs can alleviate the progression of metastatic cancer and mitigate therapeutic resistance." (PMID 34646829, 2021). "Curcumin was shown to suppress growth of bladder and pancreatic cancer cell lines through the inhibition of NFKB1-regulated proinflammatory and proproliferative gene products PTGS2 and CXCL8; both CXCL8 and PTGS2 were also found to be downregulated in pancreatic cancer." (PMID 34422220, 2021). "In addition, there was a significant correlation between serum CXCL8 concentration and CRP levels as well as with nodal involvement in pancreatic cancer patients." (PMID 34680333, 2021). "While the NF-κB pathway induces the upregulated expression of some chemokines such as CCL2, CCL5, CXCL5, CXCL8, CXCL10, CXCL12, and CX3CL1, it also participates in the antiapoptotic and proliferative effects of CCL5, CCL20, CXCL8, and CXCL12 in pancreatic cancer." (PMID 31991604, 2020). "The analytic results demonstrated that 7 upregulated (MMP9, CXCL8, ACTB, ITGB1, STAT1, TOP2A and CDK1) and 2 downregulated (GNMT and ABAT) hub genes may act as the key genes in pancreatic cancer." (PMID 31061236, 2019). "For example, MMP9 participated in pancreatic cancer angiogenesis and invasion; CXCL8 promoted invasiveness and angiogenesis in pancreatic cancer; ITGB1 was upregulated in pancreatic cancer and increased ITGB1 indicated a poor outcome; and STAT1 enhanced pancreatic cancer growth and metastasis." (PMID 31061236, 2019). "Taken together, our findings indicate that CXCL8 is not directly involved in the depletion of blood DCs in PDAC or other pancreatic tumor patients but do not exclude that the recovery of DCs may take longer time than the normalization of inflammatory factors, such as CXCL8, in blood." (PMID 20214814, 2010).
atherosclerosis (267 papers, 2006 to 2026). A disease characterized by the build-up of fatty material and calcium deposition in the arterial wall resulting in partial or complete occlusion of the arterial lumen. "Our results provide the first evidence that endothelial Ninj1 functions as a novel activator of the NF-κB/CXCL-8 axis, establishing its causal role in atherosclerosis and highlighting its potential as a targeted anti-inflammatory therapy." (PMID 41280941, 2025). "Interleukin-8 (IL-8, CXCL8) is an inflammatory agent that has been linked to the progression of atherosclerosis." (PMID 35607519, 2022). "For example, IP-10, encoded by CXCL10, and IL-8, encoded by CXCL8, belong to the C-X-C chemokine subfamily, and the literature is overflowing with evidence regarding their potential roles in causing atherosclerosis." (PMID 34941711, 2021). "CXCL8, whose expression was up-regulated by smoking in the current study, may cause tight adhesion of rolling monocytes to the endothelial cell monolayer, contributing to the development of atherosclerosis." (PMID 37189834, 2023). "Intersection of three datasets: our Ninj1-associated DEGs, atherosclerosis-related genes from GSE57691, and inflammation-associated genes from DisGeNET C0021368, yielded 11 overlapping genes including CXCL-8, TNFAIP3, and CXCL-1." (PMID 41280941, 2025). "In summary, our study establishes a novel endothelial-specific mechanism by which Ninj1 drives atherosclerosis through CXCL-8-mediated NF-κB activation." (PMID 41280941, 2025). "This study provides the first comprehensive evidence that endothelial Ninj1 promotes atherosclerosis by activating the NF-κB/CXCL-8 signaling axis." (PMID 41280941, 2025). "CXCL8 contributes to the pathology of angiogenesis, fibrosis, infection, atherosclerosis, and tumor growth." (PMID 36120307, 2022). "Patients with atherosclerosis show a higher serum level of CXCL8 and neutrophil extracellular traps (NETs)." (PMID 33503867, 2021). "This also suggests that CXCL8 can, to some extent, promote the development of atherosclerosis through the recruitment of macrophages." (PMID 35668739, 2021). "CXCL8 (also IL-8) is an important inflammatory factor involved in many inflammatory responses and diseases including the development of atherosclerosis." (PMID 33503867, 2021). "Neutrophil (PMN) leukocytes participate to the initial phases of atherosclerosis through the release of Interleukin 8 (CxCL8; IL-8) that contribute to amplification of inflammation." (PMID 24629144, 2014). "The chemokine IL-8/CXCL8 has been known to play an important role in monocyte migration into the subendothelial space in the early phase of atherosclerosis." (PMID 20107540, 2009). "Moreover, CXCL8 contributes to atherosclerosis pathogenesis through multiple mechanisms, including attracting immune cells to the lesion site, promoting the migration of vascular cells, and contributing to plaque instability." (PMID 39334887, 2024). "In our study, p.L245P-macrophages expressed higher levels of CXCL1 and CXCL8 than WT-macrophages and thus may exert a pro-inflammatory effect in the pathogenesis of atherosclerosis." (PMID 38806571, 2024). "In addition, interleukin (IL)-6, a multi-functional proinflammatory cytokine, and IL-8, another chemokine known as CXCL8, are both involved in the pathophysiology of inflammation and atherosclerosis." (PMID 38473995, 2024). "Furthermore, the CXCL8-induced neutrophil extracellular attractor increases atherosclerosis by activating NF-κB signaling and MAPK in macrophages." (PMID 36523490, 2022). "In summary, CXCL8 plays an important role not only in atherosclerosis but also in other vascular diseases and may be a promising therapeutic target." (PMID 33503867, 2021).